SNORD15B (small nucleolar RNA, C/D box 15B)
Synonyms: U15B; RNU15B
Gene: Small nucleolar RNA gene on chromosome 11 (75,404,421 to 75,404,566, forward strand). Ensembl gene ENSG00000207445.
Gene Ontology:
Biological process: RNA processing
Cellular component: nucleolus
Homologues: Orthologues: chimpanzee SNORD15 (100% identical), macaque SNORD15 (94% identical), dog SNORD15 (93% identical), pig SNORD15 (90% identical), mouse Snord15b (89% identical), rabbit SNORD15 (89% identical), guinea pig SNORD15B (88% identical), rat Snord15b (87% identical), rabbit SNORD15 (86% identical). Paralogues in human: SNORD15A (62% identical).
Diseases named in the same sentence as SNORD15B in open-access papers:
SNORD15B is named in the same sentence as 11 diseases in open-access papers, as found by Europe PMC text mining. Sharing a sentence is not in itself a finding about the gene and the disease. The quoted sentences say what the papers report.
endometrial cancer (2 papers, 2022 to 2025). Primary or metastatic malignant neoplasm involving the endometrium (mucous membrane that lines the endometrial cavity). "Pathologically, SNORD15B is significantly upregulated in endometrial cancer and associated with poor patient survival." (PMID 39851496, 2025). "In endometrial cancer, SNORD15B exerts diverse tumorigenic features by enhancing cell proliferation and migration, but also through the inhibition of apoptosis." (PMID 39851496, 2025). "Overexpression of SNORD15B also upregulated TRIM25 protein in the endometrial cancer cells in vitro and in the tumor xenograft." (PMID 36199797, 2022). "According to gene expression profiling interactive analysis (GEPIA), SNORD15B is highly expressed in acute myeloid leukemia, ovarian serous cystadenocarcinoma, endometrial cancer, and uterine carcinosarcoma." (PMID 36199797, 2022). "We also analyzed the expression levels of SNORD15B in three endometrial cancer cell lines (HEC-1B, HEC-1A, and Ishikawa)." (PMID 36199797, 2022). "Accordingly, increased SNORD15B levels are also found in different endometrial cancer cell lines." (PMID 39851496, 2025). "In addition, the ectopic expression of SNORD15B in it also promoted the malignant phenotype of the endometrial cancer cells in vivo and in vitro." (PMID 36199797, 2022). "Taken together, we can surmise that SNORD15B upregulates both TRIM25 expression and activity in endometrial cancer cells." (PMID 36199797, 2022).
chordoma (1 paper, 2025). Chordomas are rare malignant tumors arising from embryonic remnants of the notochord in axial skeleton. "The heatmap revealed that MIR5690, SNORD15B, RAB3B were highly expressed in chordoma, along with the generally reported chordoma regulators, such as KRT19, LYST, and EGFR." (PMID 40135815, 2025).
colon cancer (1 paper, 2025). "In addition to regulating ISCs under a homeostatic condition, we found that SNORD15B is highly expressed in colon cancer cells, and it may be involved in intestinal tumorigenesis." (PMID 40884233, 2025).
endometrial tumor (1 paper, 2022). "In this study, we confirmed the overexpression of SNORD15B in endometrial tumor tissues and found that the upregulation of SNORD15B was associated with a poor prognosis." (PMID 36199797, 2022).
cancer (5 papers, 2020 to 2025). A tumor composed of atypical neoplastic, often pleomorphic cells that invade other tissues. "The results of PCR showed that the mRNA expression levels of PIP5K1P1, PTTG3P, and SNORD15B in the cancer cells were significantly higher than those in normal cells." (PMID 39170694, 2024). "Thus, SNORD15B is a promising therapeutic target in endometrial and other cancers, and should be investigated further." (PMID 36199797, 2022). "Participation in this process could be considered a pro-cancer activity of this gene.Considering that SNORD15B appeared as a negative prognostic factor in microarray-based survival analyses, its functional role may be complex and warrants further investigation." (PMID 41283331, 2025).
tumor (3 papers, 2022 to 2025). "Staging data supported the presumed tumor suppressor roles of SCARNA2, SNORD15B, and RNU2-1, showing their higher expression in early-stage samples compared with more advanced stages." (PMID 41283331, 2025).
SNORD15B also shares sentences with these, for which no sentence is quoted: colon tumors (1 paper); colorectal cancer (1); prion disease (1); small intestinal adenoma (1); stomach cancer (1).